ZNF117 (zinc finger protein 117)
Description:
May be involved in transcriptional regulation.
Synonyms: h-PLK; HPF9; ERV3-1-ZNF117
Tractability: PROTAC: ubiquitination databases record sites on it.
Gene: Protein-coding gene on chromosome 7 (64,970,663 to 65,006,687, reverse strand). Ensembl gene ENSG00000152926.
Subcellular location: Nucleus
Subcellular location (Human Protein Atlas): Cytosol; Nucleoli fibrillar center
Gene Ontology:
Molecular function: DNA-binding transcription factor activity; DNA-binding transcription factor activity, RNA polymerase II-specific; RNA polymerase II cis-regulatory region sequence-specific DNA binding; zinc ion binding
Biological process: regulation of DNA-templated transcription; negative regulation of transcription by RNA polymerase II
Cellular component: nucleus
Genetic constraint (gnomAD): Loss-of-function variants: 37 observed, 41.21 expected, observed/expected ratio (o/e) 0.9, 90% interval 0.69 to 1.18. The upper end of that interval is the gene's LOEUF score, 1.18, which puts it in group 5 of 6, group 1 being the genes least tolerant of losing a copy. Missense variants: 546 observed, 557.81 expected, observed/expected ratio (o/e) 0.98, 90% interval 0.91 to 1.05. Synonymous variants: 186 observed, 186.98 expected, observed/expected ratio (o/e) 0.99, 90% interval 0.88 to 1.12.
Homologues: Paralogues in human: ZNF724 (71% identical), ZNF492 (69% identical), ZNF708 (69% identical), ZNF726 (69% identical), ZNF254 (68% identical), ZNF681 (68% identical), ZNF85 (68% identical), ZNF429 (68% identical), ZNF728 (67% identical), ZNF595 (66% identical), ZNF43 (66% identical), ZNF676 (66% identical), and 164 more.
Diseases named in the same sentence as ZNF117 in open-access papers:
ZNF117 is named in the same sentence as 8 diseases in open-access papers, as found by Europe PMC text mining. Sharing a sentence is not in itself a finding about the gene and the disease. The quoted sentences say what the papers report.
breast carcinoma (1 paper, 2024). "A number of these, such as CEBPB, ZNF117 and ZNF92, have been previously proposed as breast cancer markers and ZNF273 and ZNF727 have been reported as breast cancer hub genes." (PMID 38561804, 2024).
glioma (1 paper, 2022). A benign or malignant brain and spinal cord tumor that arises from glial cells (astrocytes, oligodendrocytes, ependymal cells). "Further analysis of several GBM public databases, including TCGA RNA-seq database, The Repository of Molecular Brain Neoplasia Data (REMBRANDT) database, and Chinese Glioma Genome Atlas (CGGA), found that the expression of ZNF117 is negatively correlated with patient survival." (PMID 35459228, 2022).
Obesity (1 paper, 2023). Accumulation of substantial excess body fat. "Zinc-finger proteins are therefore often transcription factors, act as intranuclear hormone receptors and have been implicated (including ZNF117) in obesity and in regulating adipogenesis." (PMID 37816715, 2023). "The simplest hypothesis seems to be that the functional effect of the pretermination codon on ERV3-1 is associated with obesity, but effects via ZNF117 cannot be dismissed." (PMID 37816715, 2023). "Additionally, investigation of linkage disequilibrium around rs67047829 and -omics studies comparing subjects with each genotype might elucidate a role for the ERV3-1/ZNF117 locus in obesity." (PMID 37816715, 2023).
type-2 diabetes (1 paper, 2023). "rs67047829 gives a pretermination codon in ERV3-1 which shares an exonic region and possibly promoter with ZNF117, previously associated with adiposity and type-2 diabetes." (PMID 37816715, 2023). "However, recent research has provided evidence that ZNF117 variation is associated with type-2 diabetes and adiposity, and ZNF117 is discussed first." (PMID 37816715, 2023). "rs67047829 forms a pretermination codon in ERV3-1 and potentially lies in a regulatory region of ZNF117, which has various intriguing connections with ERV3-1 and is already known to have association with cellular adipogenesis and type-2 diabetes." (PMID 37816715, 2023).
cancer (4 papers, 2017 to 2024). A tumor composed of atypical neoplastic, often pleomorphic cells that invade other tissues. "Therapy, which direct cancer cells toward non-cancer states, like ZNF117-mediated glioma stem cell differentiation, provides hope but requires further studies for optimization." (PMID 38988707, 2024). "However, further investigations are necessary in order to elucidate the role of the ERV3/ZNF117 locus in the context of cancer and other diseases as well as physiological functions of these genes." (PMID 29379485, 2017).
tumor (2 papers, 2022 to 2025). "We determined the efficacy of TMZ chemotherapy in combination with ZNF117-mediated differentiation therapy in tumor-bearing mice." (PMID 35459228, 2022). "We determined the effect of ZNF117-induced differentiation on tumor development in vivo through inoculation of engineered cells into the brains of nude mice." (PMID 35459228, 2022). "For example, ZNF117 controls the differentiation of GSCs towards the oligodendroglial lineage, while NeuroD4 and CP-673451 can trigger differentiation of GSCs into neuron-like cells, as well as reduce proliferation and invasion of tumor cells." (PMID 40191211, 2025). "We found that downregulation of ZNF117 effectively reduced the rate of cell proliferation and frequency of stem cells, induced differentiation preferentially towards oligodendroglial lineage, and inhibited tumor development in mice (P = 0.0007)." (PMID 35459228, 2022). "We found that downregulation of ZNF117 significantly prolonged the survival of tumor-bearing mice." (PMID 35459228, 2022). "The observed difference in inhibition of tumor formation between the two sgRNAs could be attributed to the fact that, compared to sgZNF117-2, sgZNF117-1 is more efficient in down-regulating ZNF117 expression and in inducing differentiation." (PMID 35459228, 2022). "We assessed if ZNF117 can be targeted for GBM treatment experimentally in tumor-bearing mice." (PMID 35459228, 2022). "Collectively, these results suggest that ZNF117 regulates GS5 cell differentiation towards oligodendroglial lineage, and downregulation of ZNF117 inhibits the proliferation, stemness, and tumor development of GSCs." (PMID 35459228, 2022). "We show that ZNF117 expression is downregulated in differentiated GSCs and that downregulation of ZNF117 induces GSC differentiation towards the oligodendroglial lineage, leading to inhibition of tumor development and increased sensitivity of GSCs to TMZ treatment." (PMID 35459228, 2022).
ZNF117 also shares sentences with these, for which no sentence is quoted: colorectal cancer (1 paper); glioblastoma (1).